RBM23 (RNA binding motif protein 23)
Description:
RNA-binding protein that acts both as a transcription coactivator and pre-mRNA splicing factor. Regulates steroid hormone receptor-mediated transcription, independently of the pre-mRNA splicing factor activity.
Synonyms: CAPERbeta; RNPC4; PP239; FLJ10482
Tractability: PROTAC: UniProt records ubiquitination sites on it; ubiquitination databases record sites on it; its protein half-life has been measured.
Gene: Protein-coding gene on chromosome 14 (22,893,204 to 22,919,182, reverse strand). Ensembl gene ENSG00000100461.
Subcellular location: Nucleus
Subcellular location (Human Protein Atlas): Intermediate filaments; Nucleoplasm
Gene Ontology:
Molecular function: protein binding; U1 snRNP binding; nucleic acid binding; RNA binding
Biological process: positive regulation of DNA-templated transcription; regulation of mRNA splicing, via spliceosome; mRNA processing; regulation of gene expression; regulation of RNA metabolic process
Cellular component: membrane; nucleus
Genetic constraint (gnomAD): Loss-of-function variants: 50 observed, 55.12 expected, observed/expected ratio (o/e) 0.91, 90% interval 0.72 to 1.15. The upper end of that interval is the gene's LOEUF score, 1.15, which puts it in group 5 of 6, group 1 being the genes least tolerant of losing a copy. Missense variants: 640 observed, 613.83 expected, observed/expected ratio (o/e) 1.04, 90% interval 0.98 to 1.11. Synonymous variants: 196 observed, 208.05 expected, observed/expected ratio (o/e) 0.94, 90% interval 0.84 to 1.06.
Homologues: Orthologues: chimpanzee RBM23 (98% identical), macaque RBM23 (96% identical), dog RBM23 (92% identical), rabbit RBM23 (91% identical), pig RBM23 (90% identical), tropical clawed frog rbm23 (67% identical). Paralogues in human: RBM39 (63% identical), NUCLEOLIN (16% identical), RBM19 (16% identical), HNRNPAB (15% identical), TIAL1 (15% identical), TIA1 (14% identical), HNRNPD (14% identical), MSI1 (14% identical), MSI2 (13% identical), HNRNPDL (13% identical), DAZAP1 (13% identical), HNRNPA2B1 (13% identical), and 24 more.
Diseases named in the same sentence as RBM23 in open-access papers:
RBM23 is named in the same sentence as 6 diseases in open-access papers, as found by Europe PMC text mining. Sharing a sentence is not in itself a finding about the gene and the disease. The quoted sentences say what the papers report.
bladder cancer (1 paper, 2016). "Expression of IER5 and cancer-associated HSF1 target genes (RBM23 and EIF4A2) showed a significant association in bladder cancer (r = 0.64 and p < 0.0001 for RBM23, and r = 0.54 and p < 0.0001 for EIF4A2)." (PMID 26754925, 2016).
breast carcinoma (1 paper, 2016). "In addition, an even higher association of IER5 and RBM23 and EIF4A2 were found in breast cancer patients (r = 0.75 and p < 0.0001 for RBM23, and r = 0.65 and p < 0.0001 for EIF4A2)." (PMID 26754925, 2016).
hepatocellular carcinoma (1 paper, 2021). A malignant tumor that arises from hepatocytes. "In this study, we identified RBM23 as a new molecule that promotes tumor angiogenesis, which provides a new perspective for us to deepen our understanding of angiogenesis in hepatocellular carcinoma." (PMID 33791378, 2021). "In order to investigate the role of RBM23 in hepatocellular carcinoma progression, we examined its expression in hepatocellular carcinomas and then compared with the adjacent normal tissues by western blotting assays." (PMID 33791378, 2021). "Based on this, we launched relevant research and initially identified RBM23 as a factor that promotes microvascular proliferation in hepatocellular carcinoma." (PMID 33791378, 2021). "We propose that RBM23 may serve as a promising prognostic marker for hepatocellular carcinoma, and knocking down CHIP may be a novel strategy for antiangiogenesis therapy for human HCC." (PMID 33791378, 2021). "In this study, RBM23 did not affect the activation and expression of IkBa in our study; unexpectedly, we found that RBM23 could improve the level of RelA/p65 mRNA, thereby increasing the activity of the NF-κB signaling pathway to promote the angiogenesis of hepatocellular carcinoma." (PMID 33791378, 2021). "In summary, this study demonstrates that RBM23 regulates the activity of the NF-κB signaling pathway in HCC via directly targeting RelA/p65; these data revealed the RBM23-RelA/p65-NF-κB axis as a mechanism of promoting the angiogenesis in hepatocellular carcinoma." (PMID 33791378, 2021). "We observed a strong positive correlation between the levels of RBM23 and MVD, which was also verified by western blotting assays in the previous queue, suggesting that RBM23 might drive the development of hepatocellular carcinoma by affecting tumor angiogenesis." (PMID 33791378, 2021).
liver cancer (1 paper, 2021). An epithelial or non-epithelial malignant neoplasm that arises from the liver. "This suggested that RBM23 might be involved in the development of liver cancer." (PMID 33791378, 2021).
tumor (2 papers, 2014 to 2021). "Results showed that the protein levels of RBM23 were significantly higher in most tumor samples when compared with the paired normal tissues." (PMID 33791378, 2021). "This further showed that RBM23 promoted tumor angiogenesis by activating the NF-κB signaling pathway." (PMID 33791378, 2021). "The results obtained proved that RBM23 could promote tumor neovascularization in vivo." (PMID 33791378, 2021). "To investigate the correlation between RBM23 levels and MVD in HCCs, we detected the expression levels of RBM23 and CD31 in tumor specimens from 32 HCC patients by IHC staining in another queue." (PMID 33791378, 2021). "Heat shock-activated HSF1 is mainly responsive to the expression of heat shock proteins, while activation of HSF1 in tumor tissues is predominantly responsible for controlling the expression of non-heat shock proteins, e.g. CKS2, LY6K, RBM23, CCT6A, CKS1B, ST13 and EIF4A2." (PMID 25199534, 2014).
RBM23 also shares sentences with these, for which no sentence is quoted: cancer (2 papers).